LPL (lipoprotein lipase)
Diseases named in the same sentence as LPL in open-access papers (continued):
Sharing a sentence is not in itself a finding about the gene and the disease.
Insulin resistance (continued). "LPL activity is enhanced by insulin and, on the contrary, attenuated by insulin resistance." (PMID 36979405, 2023). "Additionally, through the activation of FOXO1, insulin resistance promotes the production of apoC3, an inhibitor of LPL." (PMID 37009872, 2023). "The literature suggests oxidation of free fatty acids, systemic metabolic acidosis, and inhibition of lipoprotein lipase in adipose tissue as the mechanism of this phenomenon, which may lead to the development of insulin resistance." (PMID 36830821, 2023). "Furthermore, increased HSP72 expression in skeletal muscle was associated with an increase in the expression of lipoprotein lipase (LPL), demonstrating that increased mitochondria in skeletal muscle leads to the suppression of insulin resistance." (PMID 37238736, 2023). "They related this correlation to insulin resistance, which decreases glycogen synthesis and protein catabolism while inhibiting lipoprotein lipase in adipocytes, resulting also in defects in fatty acid metabolism and increasing very low density lipoprotein (VLDL)." (PMID 38084237, 2023). "Finally, at the end of gestation, it is worth noting that the LPL activity is decreased due to the presence of insulin resistance." (PMID 36768809, 2023). "It is known that in patients with acromegaly, the inhibition of the activity of lipoprotein lipase and lecithin–cholesterol acyltransferase under the influence of GH and insulin resistance results in an increase in triglycerides and a decrease in the HDL fraction." (PMID 37446150, 2023). "LPL activity is increased by insulin and decreased by insulin resistance." (PMID 37009872, 2023). "Insulin resistance increases TG by increasing hepatic VLDLs and low levels of lipoprotein lipase." (PMID 38024366, 2023). "The normal insulin-mediated stimulation of LPL activities is interrupted by insulin resistance." (PMID 37007365, 2023). "Also due to prevailing insulin resistance, the formation of smaller VLDL particles, by LPL, is decreased, and likely hence weaker associations were observed between smaller VLDL lipids and insulin resistance." (PMID 36979405, 2023). "Although the exact mechanism of dyslipidemia in T2DM patients is uncertain, insulin resistance may impair lipoprotein lipase activity, which is thought to be crucial in the onset of diabetic dyslipidemia." (PMID 36404351, 2022). "Insulin resistance reduces lipoprotein lipase (LPL) activity." (PMID 35915785, 2022). "One hypothesis is that this increase is a secondary consequence of another side effect of this drug, which is insulin resistance and hyperinsulinemia, as well as a decreased synthesis of lipoprotein lipase (LPL)." (PMID 36009482, 2022). "We hypothesize that liver-specific LPL overexpression suppresses hepatic lipid accumulation, leading to the improvement of insulin resistance." (PMID 36099304, 2022). "As LPL is activated by insulin also in BAT, and LPL activation is compromised by insulin resistance, reduced LPL levels in cold-housed Cyp7b1−/− mice might result from their insulin resistance." (PMID 35478959, 2022). "However, a differential involvement and cross-talk of Angptl3 with fatty acids in the context of lipolysis, lipoprotein lipase pathway, insulin resistance, and inflammation is highly probable." (PMID 34951653, 2022). "Insulin resistance decreases the activity of LPL, which catabolizes TG-rich lipoproteins." (PMID 35408799, 2022). "Taken together, attenuation of lipid accumulation by Ad vector-mediated liver-specific overexpression of LPL in the liver may contribute to maintaining mitochondrial function and improving insulin resistance." (PMID 36099304, 2022). "Researches have shown that patients with diabetes, obesity, or metabolic syndrome due to insulin resistance tend to have low HDL-C because of lower lipoprotein lipase activity and triglyceride enrichment, but the mechanism is still unknown." (PMID 35902759, 2022).
Insulin resistance (continued). "HDL results from the degradation of VLDL by lipoprotein lipase, which may explain a decreased HDL concentration in peripheral blood under the conditions of reduced lipoprotein lipase activity in insulin resistance." (PMID 34745660, 2021). "Hence, transgenic mice with muscle-specific LPL overexpression exhibited skeletal muscle and whole-body insulin resistance, and variations in the LPL gene have been reported to play a role in determining insulin resistance in Mexican Americans." (PMID 34356640, 2021). "Reductions in hepatic lipase and cholesterol ester transfer protein by the suppression of inflammation following H. pylori eradication or the reduction in the activity of lipoprotein lipase by obesity (insulin resistance) can lead to an increase of TG following H. pylori eradication." (PMID 33668848, 2021). "Taking into consideration the repression of adipocyte ANGPTL4 mRNA by insulin, the upregulation of ANGPTL4 in insulin resistance may contribute to the postprandial dyslipidemia in insulin-resistant individuals via inhibition of LPL." (PMID 32504883, 2020). "Furthermore, a recent study showed that Angptl8 antisense oligonucleotides protect fat-fed mice against hepatic steatosis and insulin resistance by promoting adipose lipoprotein lipase (LPL) activity and inhibiting ectopic lipid accumulation." (PMID 32299395, 2020). "However, the effect of LPL inhibition on insulin resistance (IR) and lipid metabolism remains ambiguous." (PMID 31234537, 2019). "Additionally, genetic alterations in these genes are strongly involved, especially mutations in five genes (DGAT1, FASN, LPL, IRS2, and YWHAZ), in lipid synthesis, insulin resistance, and cancer progression." (PMID 31717414, 2019). "A poor activity of the enzyme LPL has previously been linked to insulin resistance and diabetes, in accordance with our finding of a negative association between LPL concentrations and prevalent diabetes." (PMID 31446444, 2019). "In contrast, the disruption of LPL in skeletal muscle results in reductions in lipid storage and increased myocyte insulin signalling, together with marked insulin resistance in other tissues, leading finally to obesity and systemic insulin resistance." (PMID 31208038, 2019). "Moreover, it is also important to remark that mice with muscle-specific LPL overexpression generated a muscle-selective insulin resistance." (PMID 31208038, 2019). "All of these alterations imply the insulin resistance was aggravated by LPL inhibition." (PMID 31234537, 2019). "The enhancement of insulin resistance in the context of elevated ANGPTL4 levels could be explained by the selective inhibition of LPL in white adipose tissue, which leads to an ectopic lipid accumulation and insulin resistance." (PMID 30944669, 2019). "Insulin resistance also decreases lipoprotein lipase activity, a major mediator of VLDL clearance." (PMID 30170598, 2018). "Moreover, a lack of LPL in skeletal muscles has been reported to result in insulin resistance in other key metabolic tissues, while increased LPL activity has been reported to improve insulin resistance and reduce adipose accumulation in transgenic rabbits." (PMID 29216237, 2017). "Regulation of the adipose tissue LPL is significantly affected in individuals with insulin resistance in the postprandial period, and the presumed impairment could contribute to atherogenic dyslipidemia." (PMID 29216237, 2017). "Although not directly measured in this study, subjects with MetS may have decreased expression of LPL as a consequence of insulin resistance." (PMID 27686975, 2016). "High levels of TNF-α have been shown to inhibit lipoprotein lipase activity in vitro and enhance the production of liver-derived TRL and adiposity has been reported to potentiate the effects of the TNFA polymorphism on lipid metabolism and insulin resistance." (PMID 27456841, 2016).
Insulin resistance (continued). "Moreover, liver-specific overexpression of LPL leads to a 2-fold increase in liver TG content and insulin resistance in mice." (PMID 27234787, 2016). "Insulin resistance can also decline the activity of lipoprotein lipase." (PMID 26891315, 2016). "Some previous studies have shown that insulin resistance is associated with increased fatty acids levels released by adipose tissue and elevated VLDL-TG secretion in the hepatocytes and lower adipose tissue lipoprotein lipase activity." (PMID 26609520, 2015). "Low adiponectin plasma levels are associated with augmented VLDL catabolism and coupled with reduced LPL activity in adipose tissue independently of insulin resistance, suggesting a possible direct action of adiponectin on lipid metabolism, independent of its effects on insulin sensitivity." (PMID 25725623, 2015). "Further studies have shown that insulin resistance may lead to overexpression of the lipoprotein lipase (LPL) gene, thereby enabling continuous generation of free fatty acids in the liver." (PMID 24816278, 2014). "Islet β-cell dysfunction can also lead to elevated TG levels, the mechanism could be that under the insulin resistance condition, decrease in LPL activity and excessive increase in VLDL level will eventually reduce the decomposition in chylomicrons (CM)." (PMID 22876749, 2012). "An increased GPIHBP1 level might compensate for decreased LPL levels due to insulin resistance." (PMID 40507147, 2025). "In addition, the favorable impact of pemafibrate on insulin resistance may be also involved in the reduction of dietary fatty acids via its effect on lipoprotein lipase." (PMID 40375947, 2025). "Moreover, LPL activity in skeletal muscle negatively correlates with plasma insulin levels and could be lowered by insulin resistance." (PMID 38674801, 2024). "Furthermore, insulin resistance or hyperinsulinemia could influence the functions of lipoprotein lipase in adipose tissue, elevating both the quantity and activities of hepatic triglyceride lipase." (PMID 38398871, 2024). "Even though insulin resistance may also dampen the uptake of TG‐derived FAs because of decreased LPL activity, we do expect that determining the uptake of TG‐derived FAs as a measure of BAT volume and activity will greatly enhance the sensitivity and specificity." (PMID 33945228, 2021). "On the other hand, high prolactin levels may also contribute to insulin resistance, through its effects on dopamine down-regulation and leptin resistance in the central nervous system and the inhibition of lipoprotein lipase activity and adiponectin secretion in adipose tissue." (PMID 32180760, 2020). "In the present study, we observed that postprandial triglyceride concentrations in KPDM remained elevated, suggesting delayed clearance of exogenous triglyceride-rich lipoproteins, which may result from reduced lipoprotein lipase activity driven by insulin resistance." (PMID 25275325, 2014). "In addition, previous studies have suggested that muscle activity of lipoprotein lipase (LPL) is related to insulin resistance and that insulin may downregulate the activity of lipoprotein lipase in skeletal muscle." (PMID 24098655, 2013). "Results: miR-122 was found to negatively regulate genes involved in lipid metabolism, insulin signaling, and inflammatory pathways, including PPARGC1A, PPARA, LPL, TLR4, and HMGCR, contributing to insulin resistance and liver dysfunction." (PMID 41595656, 2026). "This study showed that reciprocal fluctuations in LPL and HTGL levels in the peripheral bloodstream are correlated with insulin resistance in middle-aged Japanese individuals." (PMID 40507147, 2025). "In this study, in PLH, data were found that reflected increased insulin resistance, with low HDL-C and low LPL in peripheral blood stream." (PMID 41156460, 2025).
Insulin resistance (continued). "Low HDL-C and low LPL levels in PLH are likely due to two mechanisms: a direct effect of ARVs on reducing LPL expression, and an indirect effect mediated by increased insulin resistance." (PMID 41156460, 2025). "Reduced expression of lipid metabolism genes (LPL, ACC, FASN, ACSS) in patients with insulin resistance in VAT indicates significant disturbances in lipid handling." (PMID 40806527, 2025). "Further, these results indicate that reciprocal fluctuations in LPL and HTGL levels affect LDL-C metabolism in the peripheral bloodstream via their correlation with insulin resistance." (PMID 40507147, 2025). "Circulating levels of LPL and HTGL are more affected by insulin resistance in females than in males." (PMID 40507147, 2025). "To identify such mechanisms, we analyzed LPL, GPIHBP1, HTGL and insulin resistance in middle-aged Japanese individuals." (PMID 40507147, 2025). "Hypothetically, diminished LPL activity regarding T2D could augment circulating triglyceride concentrations and increase lipotoxicity, characterized by the adverse impact of excess fatty acids on insulin signaling and glucose homeostasis and worsening insulin resistance." (PMID 41373652, 2025). "The correlation between reciprocal fluctuations in LPL, GPIHBP1, and HTGL and insulin resistance was evident under physiological conditions and was attenuated in IFG." (PMID 40507147, 2025). "In PLH, patients with high HOMA-βlevels were characterized by high insulin resistance, as indicated by high HOMA-IR, fasting insulin, body fat mass, WC, BMI, and TG, and low LPL and HDL-C." (PMID 41156460, 2025). "It has been reported that PPARα activation upregulates its target genes (LPL, ACOX1, and CPT-1a) expression, enhancing lipid degradation and fatty acid oxidation, which ameliorates hepatic steatosis, dyslipidemia, and insulin resistance." (PMID 39942052, 2025). "This study showed that reciprocal fluctuations in LPL, GPIHBP1, and HTGL levels in the peripheral bloodstream are correlated with insulin resistance." (PMID 40507147, 2025). "High TG observed in insulin resistance is induced by hepatic over-production of VLDL and reduced VLDL degradation by impaired lipoprotein lipase." (PMID 39201071, 2024). "Adipose tissue dysfunction and insulin resistance escalate lipolysis and FFA release, leading to decreased lipoprotein lipase activity and increased cholesteryl ester transfer protein expression." (PMID 39175570, 2024). "In distinction, the hTg/loHDL phenotype occurs with insulin resistance in the liver that leads to up-regulation of Apo CIII and subsequent inhibition of lipoprotein lipase (LPL)." (PMID 39286650, 2024). "On the other hand, insulin resistance induces dyslipidemia by affecting the low-density lipoprotein receptor (LDL) and consequently removing LDL, decreasing lipoprotein lipase (LPL) activity, and overactivating liver lipase (HL)." (PMID 38892574, 2024). "Patients with hepatic steatosis and insulin resistance have increased levels of circulating ApoC-III, which is a strong inhibitor of LPL." (PMID 38195587, 2024). "The relationship between body fat and lipid profiles may be associated with insulin resistance and increased free fatty acids, a condition leading to the formation of large TG-rich VLDL particles, which alters the expression of key enzymes in the plasma, such as decreased lipoprotein lipase." (PMID 36673920, 2023). "Additionally, triglyceride and glucose clearance may have been worse among those with larger waists due to insulin resistance and less available lipoprotein lipase; moreover, glycerol from visceral fat may have been a contributor to circulating glucose among those with visceral adiposity." (PMID 35057419, 2022). "In insulin resistance, TG-rich lipoproteins such as VLDL, IDL, and CM remnants increase, and HDL decreases due to reduced LPL activity." (PMID 35408799, 2022).
Insulin resistance (continued). "Lowered insulin-dependent decrease in lipoprotein lipase (LPL) activity in adipose tissue and subsequent insulin resistance are observed during the pregnancy." (PMID 35126178, 2021). "Patients with obesity or MS accompanied by insulin resistance tend to have TG enrichment and low HDL-C level due to decreased lipoprotein lipase activity." (PMID 33692759, 2021). "Another possible mechanism underlying the adiponectin-induced up-regulation of HDL-C is the activation of lipoprotein lipase (LPL) by adiponectin and/or the improvement of insulin resistance, which can also reduce TG." (PMID 30857216, 2019). "Studies have shown that LPL and FASN over-expression result in higher fat mass and more insulin resistance." (PMID 27777604, 2016). "Reductions in adipose tissue lipoprotein lipase (LPL) mass and activity have also been observed in the presence of obesity-mediated insulin resistance." (PMID 25061524, 2014). "LPL activity is crucial in VLDL and remnant lipoprotein metabolism, and is often suppressed in the presence of insulin resistance." (PMID 24098467, 2013). "Accordingly an IRS1 knock-out mouse model displayed a MetS like phenotype with insulin resistance, increased blood pressure, increased triglycerides, decreased HDL cholesterol and decreased LPL activity." (PMID 23101478, 2012). "In old, obese rats that showed signs of insulin resistance, the responses of ANGPTL4 and GPIHBP1 mRNA and of LPL activity were severely blunted (at 26 weeks of age) or almost abolished (at 52 weeks of age)." (PMID 23176178, 2012). "Excessive circulating lipids from the HF–HS diet may have stimulated LPL overexpression, and it has been demonstrated that tissue-specific overexpression of LPL in skeletal muscle and liver increases cellular stores of triglycerides and leads to insulin resistance." (PMID 22762794, 2012). "Like LPL, circulating HTGL levels are more affected by insulin resistance in females than in males." (PMID 40507147, 2025). "Also, HDL‐c concentration is decreased by the production of fatty acids in the liver, while lipoprotein lipase function is blocked through increased production of apolipoprotein CIII, especially in the presence of insulin resistance." (PMID 38726395, 2024). "Therefore, it is conceivable that neurohormonal activation, inflammation, insulin resistance, and congestion, the hallmarks of the HF pathophysiology, modulate the TG and PL content of circulating VLDL through modulation of LPL and EL activity." (PMID 36291751, 2022). "However, chitosan supplementation decreased plasma tumor necrosis factor (TNF)-α, insulin levels, alanine aminotransferase (ALT) activity, insulin resistance (HOMA-IR), and adipose tissue lipoprotein lipase activity." (PMID 34443619, 2021). "One study in lipodystrophic patients with metabolic syndrome argued that their insulin resistance could reduce HDL production and increase its metabolism while high VLDL levels could be related to low lipoprotein lipase levels." (PMID 33411809, 2021). "VAT ANGPTL4 mRNA was not correlated with VAT LPL expression although increased LPL mRNA expression was associated with higher FSI (r = 0.46, p = 0.019) and insulin resistance (HOMA-IR: r = 0.44, p= 0.024)." (PMID 33003532, 2020). "This combined research led to a total placement in the top 400 in 2018 when it was discovered that disinhibition of adipose tissue lipoprotein lipase is a novel therapeutic modality of ANGPTL8, to enhance adipose lipid uptake and treat non-alcoholic fatty liver disease and insulin resistance." (PMID 32542027, 2020). "The excessively produced lipoprotein (VLDL, IDL, LDL) and decreased LPL due to insulin resistance have high TG content and are not efficiently absorbed by the liver, thus creating small dense LDLs, which are the main constituents for atherosclerosis." (PMID 31212747, 2019).